RNU6-1001P (RNA, U6 small nuclear 1001, pseudogene)
Gene: Small nuclear RNA gene on chromosome 2 (155,089,439 to 155,089,538, reverse strand). Ensembl gene ENSG00000223197.
Homologues: Orthologues: chimpanzee U6 (99% identical), macaque U6 (98% identical), rat U6 (83% identical), dog U6 (81% identical), pig U6 (80% identical), mouse Gm23003 (78% identical), guinea pig U6 (77% identical), mouse Gm22686 (76% identical). Paralogues in human: RNU6-1060P (87% identical), RNU6-921P (87% identical), RNU6-536P (85% identical), RNU6-1131P (84% identical), RNU6-1065P (83% identical), RNU6-1152P (83% identical), RNU6-116P (83% identical), RNU6-15P (83% identical), RNU6-19P (83% identical), RNU6-45P (83% identical), RNU6-487P (83% identical), RNU6-633P (83% identical), and 1283 more.